PPP1R10 (protein phosphatase 1 regulatory subunit 10)
Description:
Substrate-recognition component of the PNUTS-PP1 protein phosphatase complex, a protein phosphatase 1 (PP1) complex that promotes RNA polymerase II transcription pause-release, allowing transcription elongation. Promoter-proximal pausing by RNA polymerase II is a transcription halt following transcription initiation but prior to elongation, which acts as a checkpoint to control that transcripts are favorably configured for transcriptional elongation. The PNUTS-PP1 complex mediates the release of RNA polymerase II from promoter-proximal region of genes by catalyzing dephosphorylation of proteins involved in transcription, such as AFF4, CDK9, MEPCE, INTS12, NCBP1, POLR2M/GDOWN1 and SUPT6H. The PNUTS-PP1 complex also regulates RNA polymerase II transcription termination by mediating dephosphorylation of SUPT5H in termination zones downstream of poly(A) sites, thereby promoting deceleration of RNA polymerase II transcription. PNUTS-PP1 complex is also involved in the response to replication stress by mediating dephosphorylation of POLR2A at 'Ser-5' of the CTD, promoting RNA polymerase II degradation. The PNUTS-PP1 complex also plays a role in the control of chromatin structure and cell cycle progression during the transition from mitosis into interphase (By similarity). PNUTS-PP1 complex mediates dephosphorylation of MYC, promoting MYC stability by preventing MYC ubiquitination by the SCF(FBXW7) complex. In addition to acts as a substrate-recognition component, PPP1R10/PNUTS also acts as a nuclear targeting subunit for the PNUTS-PP1 complex. In some context, PPP1R10/PNUTS also acts as an inhibitor of protein phosphatase 1 (PP1) activity by preventing access to substrates, such as RB.
Synonyms: CAT53; FB19; PNUTS; p99; PP1R10; R111
Tractability: PROTAC: UniProt records ubiquitination sites on it; ubiquitination databases record sites on it; its protein half-life has been measured.
Gene: Protein-coding gene on chromosome 6 (30,600,400 to 30,618,612, reverse strand). Ensembl gene ENSG00000204569.
Subcellular location: Nucleus; Chromosome
Subcellular location (Human Protein Atlas): Nucleoplasm; Nuclear bodies
Pathways (Reactome):
Metabolism of RNA: mRNA Polyadenylation
Gene Ontology:
Molecular function: enzyme-substrate adaptor activity; protein binding; protein phosphatase inhibitor activity; protein phosphatase regulator activity; RNA binding; metal ion binding; protein phosphatase 1 binding
Biological process: negative regulation of cardiac muscle cell apoptotic process; negative regulation of mitotic DNA damage checkpoint; negative regulation of transcription elongation by RNA polymerase II; positive regulation of telomere maintenance; positive regulation of termination of RNA polymerase II transcription, poly(A)-coupled; positive regulation of transcription elongation by RNA polymerase II; protein stabilization; RNA polymerase II promoter clearance; protein import into nucleus
Cellular component: chromatin; chromosome; chromosome, telomeric region; nuclear body; nucleoplasm; nucleus; PTW/PP1 phosphatase complex
Genetic constraint (gnomAD): Loss-of-function variants: 15 observed, 95.7 expected, observed/expected ratio (o/e) 0.16, 90% interval 0.1 to 0.24. The upper end of that interval is the gene's LOEUF score, 0.24, which puts it in group 1 of 6, group 1 being the genes least tolerant of losing a copy. Missense variants: 947 observed, 1,260.1 expected, observed/expected ratio (o/e) 0.75, 90% interval 0.71 to 0.79. Synonymous variants: 430 observed, 448.78 expected, observed/expected ratio (o/e) 0.96, 90% interval 0.88 to 1.04.
Homologues: Orthologues: chimpanzee PPP1R10 (99% identical), macaque PPP1R10 (99% identical), dog PPP1R10 (96% identical), pig PPP1R10 (95% identical), mouse Ppp1r10 (90% identical), rat Ppp1r10 (88% identical), rabbit PPP1R10 (81% identical), guinea pig PPP1R10 (81% identical), tropical clawed frog ppp1r10 (58% identical), zebrafish ppp1r10 (49% identical), Drosophila melanogaster PNUTS (22% identical). Paralogues in human: ZC3H18 (14% identical), PRR3 (9% identical).
Diseases named in the same sentence as PPP1R10 in open-access papers:
PPP1R10 is named in the same sentence as 27 diseases in open-access papers, as found by Europe PMC text mining. Sharing a sentence is not in itself a finding about the gene and the disease. The quoted sentences say what the papers report.
breast carcinoma (10 papers, 2011 to 2025). "In the current study we identify the role of the AEP/ATR/PPP1R10 axis in genotoxic stress tolerance in breast cancer patients." (PMID 40012043, 2025). "Here, we demonstrate that AEP plays a dual role in the resistance of breast cancer (BC) patients to genotoxic stress through the regulation of ATR and PPP1R10 levels, key DNA repair effectors." (PMID 40012043, 2025).
Down syndrome (1 paper, 2025). "Another EWAS performed in drops of blood collected at birth in children with Down Syndrome (DS) showed that HOPX, SMIM24, and PPP1R10 were abnormally methylated in children with DS who developed ALL." (PMID 41226303, 2025).
HCMV infection (1 paper, 2024). "Our findings indicate that HCMV infection disrupts PP1 function through the temporal dysregulation of at least nine recognized regulatory subunits, PPP1R10, PPP1R7, YLPM1, PPP1R11, PPP1R9A, PPP1R8 (NIPP1), PPP1R9B, PPP1R12C, and URI1." (PMID 39772267, 2024).
type 1 diabetes (1 paper, 2011). "The detailed examination of the relationship between gene GNL1 and gene PPP1R10 may provide some new insights in studying the causes of type 1 diabetes." (PMID 21569557, 2011).
tumor (11 papers, 2007 to 2025). "Loss of Kindlin-1 leads to increased tumor growth, with many of the most upregulated genes in the Kindlin-1-depleted tumors linked to cancer prognosis, including Cstf2, Ppp1r10, Nr4a1 and Ggt1." (PMID 38982038, 2024). "Cell cycle—PPP1R10, encoding for a protein phosphatase involved in cell cycle progression, DNA repair and apoptosis, is part of a gene signature related to tumor downsizing after nCRT." (PMID 32580435, 2020).
cancer (10 papers, 2017 to 2025). A tumor composed of atypical neoplastic, often pleomorphic cells that invade other tissues. "In various cancer cell lines, siRNA-mediated PPP1R10 knockdown results in tumor suppressor PTEN release from nuclear sequestration." (PMID 34112754, 2021). "To determine whether MYC and its putative interactor, PP1/PNUTS, are both expressed in cancer, we examine the amplification status of the MYC gene, as well as genes of the PP1/PNUTS holoenzyme (PPP1CA, PPP1CB, PPP1CC, and PPP1R10) in The Cancer Genome Atlas (TCGA) datasets." (PMID 30158517, 2018).
infection (1 paper, 2024). The state of being infected such as from the introduction of a foreign agent such as serum, vaccine, antigenic substance or organism. "Specifically, the interaction with PPP1R10 (PNUTS) was found to be most enriched over the course of the infection, whereas the interaction with URI1 (PPP1R19) showed the most pronounced decrease." (PMID 39772267, 2024).
PPP1R10 also shares sentences with these, for which no sentence is quoted: acute myocardial infarction (2 papers); colon cancer (2); prostate carcinoma (2); Alzheimer disease (1); breast (1); diabetes (1); embryonal carcinoma (1); endothelial dysfunction (1); esophageal carcinomas (1); glioblastoma (1); influenza (1); leukemia (1); lung adenocarcinoma (1); lung carcinoma (1); lymphoma (1); ovarian carcinoma (1); renal cell cancer (1); squamous cell lung carcinoma (1); triple-negative breast carcinoma (1); uterine carcinoma (1).